CREBZF (CREB/ATF bZIP transcription factor)
Description:
Strongly activates transcription when bound to HCFC1. Suppresses the expression of HSV proteins in cells infected with the virus in a HCFC1-dependent manner. Also suppresses the HCFC1-dependent transcriptional activation by CREB3 and reduces the amount of CREB3 in the cell. Able to down-regulate expression of some cellular genes in CREBZF-expressing cells.
Synonyms: ZF; SMILE
Tractability: PROTAC: ubiquitination databases record sites on it.
Gene: Protein-coding gene on chromosome 11 (85,657,742 to 85,682,908, reverse strand). Ensembl gene ENSG00000137504.
Subcellular location: Nucleus
Subcellular location (Human Protein Atlas): Mitochondria; Nucleoplasm
Gene Ontology:
Molecular function: identical protein binding; protein binding; DNA binding; DNA-binding transcription factor activity, RNA polymerase II-specific; DNA-binding transcription factor activity
Biological process: negative regulation of DNA-templated transcription; negative regulation of gene expression, epigenetic; positive regulation of transcription by RNA polymerase II; regulation of transcription by RNA polymerase II; response to virus; ATF6-mediated unfolded protein response; integrated stress response signaling; regulation of DNA-templated transcription
Cellular component: nucleus; RNA polymerase II transcription regulator complex; chromatin
Genetic constraint (gnomAD): Loss-of-function variants: 8 observed, 19.56 expected, observed/expected ratio (o/e) 0.41, 90% interval 0.24 to 0.74. The upper end of that interval is the gene's LOEUF score, 0.74, which puts it in group 3 of 6, group 1 being the genes least tolerant of losing a copy. Missense variants: 518 observed, 501.27 expected, observed/expected ratio (o/e) 1.03, 90% interval 0.96 to 1.11. Synonymous variants: 270 observed, 233.13 expected, observed/expected ratio (o/e) 1.16, 90% interval 1.05 to 1.28.
Homologues: Orthologues: chimpanzee CREBZF (99% identical), macaque CREBZF (98% identical), pig CREBZF (93% identical), rabbit CREBZF (90% identical), guinea pig CREBZF (89% identical), rat Crebzf (86% identical), mouse Crebzf (83% identical), tropical clawed frog crebzf (28% identical), zebrafish crebzf (27% identical).